USP17L4 (ubiquitin specific peptidase 17 like family member 4)
Tractability: No criterion of Open Targets' tractability assessment is met for any kind of drug.
Gene: Protein-coding gene on chromosome 8 (7,337,115 to 7,338,707, forward strand). Ensembl gene ENSG00000236125.
Subcellular location: Nucleus; Endoplasmic reticulum
Pathways (Reactome):
Metabolism of proteins: Ub-specific processing proteases
Gene Ontology:
Molecular function: cysteine-type deubiquitinase activity
Biological process: regulation of apoptotic process; protein deubiquitination
Cellular component: endoplasmic reticulum; nucleus
Genetic constraint (gnomAD): Loss-of-function variants: 5 observed, 3.18 expected, observed/expected ratio (o/e) 1.57, 90% interval 0.73 to 1.94. That is too few expected variants to judge how well the gene tolerates losing a copy. Missense variants: 41 observed, 30.44 expected, observed/expected ratio (o/e) 1.35, 90% interval 1.05 to 1.74. Synonymous variants: 11 observed, 10.73 expected, observed/expected ratio (o/e) 1.02, 90% interval 0.64 to 1.66.
Homologues: Paralogues in human: USP17L8 (98% identical), USP17L3 (97% identical), USP17L1 (97% identical), USP17L2 (96% identical), USP17L17 (94% identical), USP17L11 (94% identical), USP17L20 (94% identical), USP17L22 (94% identical), USP17L18 (93% identical), USP17L24 (93% identical), USP17L25 (93% identical), USP17L26 (93% identical), and 59 more.